RNU6-263P (RNA, U6 small nuclear 263, pseudogene)
Gene: Small nuclear RNA gene on chromosome 6 (18,306,973 to 18,307,079, reverse strand). Ensembl gene ENSG00000200681.
Homologues: Orthologues: chimpanzee U6 (100% identical), macaque U6 (93% identical), rabbit U6 (79% identical), dog U6 (71% identical). Paralogues in human: RNU6-1251P (91% identical), RNU6-16P (91% identical), RNU6-28P (91% identical), RNU6-29P (91% identical), RNU6-33P (91% identical), RNU6-1 (90% identical), RNU6-116P (90% identical), RNU6-11P (90% identical), RNU6-15P (90% identical), RNU6-2 (90% identical), RNU6-37P (90% identical), RNU6-39P (90% identical), and 1284 more.